CXCL12 (C-X-C motif chemokine ligand 12)
Diseases named in the same sentence as CXCL12 in open-access papers (continued):
Sharing a sentence is not in itself a finding about the gene and the disease.
ovarian carcinoma (continued). "In ovarian cancer patients, tumor-associated inflammatory mediator prostaglandin E2 (PGE2) induced the production of CXCL12(SDF1) in TME and functional expression of CXCR4 on MDSCs, which further attracted MDSCs into the TME." (PMID 35267547, 2022). "The CXCL12 has been seen as a strong accelerant to promote metastasize and invasion in ovarian cancer." (PMID 35756990, 2022). "CXCL12 is present in 95% of ovarian cancer ascites, while CXCR4 is the only chemokine receptor expressed in ovarian cancer cells." (PMID 35406620, 2022). "CXCR4 can serve as an independent prognostic factor in ovarian cancer, revealing a close relationship between the chemokine axis CXCL12/CXCR4 and ovarian malignancies, which has been reported in many studies." (PMID 35681259, 2022). "The results indicate significant changes in the expression of both CCL7 and CXCL12 in fibroblasts after treatment with exosomes derived from ovarian cancer cells." (PMID 36012171, 2022). "A study based on the single-cell dissection of cellular components in ovarian cancer revealed that CAFs-T cells cross-talk relies on the CXCL12/14-CXCR4 axis." (PMID 36119108, 2022). "In our study, we observed an increase in the expression of VEGFA and three cytokines (IL18, CCL7 and CXCL12) in fibroblasts after treatment with exosomes derived from ovarian cancer cells." (PMID 36012171, 2022). "Another chemokine receptor, CXCR4, is overexpressed in human ovarian cancer and its ligand CXCL12 has been shown to be present in ascitic fluid collected from patients with ovarian carcinoma." (PMID 35625966, 2022). "miR-448 inhibits cell proliferation, migration, and invasion in ovarian cancer by targeting CXCL12 expression." (PMID 35647303, 2022). "Exosomes from both examined ovarian cancer lines contributed to the increase in the expression of CXCL12 in fibroblasts." (PMID 36012171, 2022). "CXCL12/CXCR4 promotes invasion of ovarian cancer cells by suppressing ARHGAP10 expression via the VEGF/VEGFR2 signaling pathway." (PMID 34907282, 2021). "CXCL12 expression was also increased in ovarian cancer cells compared to normal ovarian epithelial cells, which was thought to stimulate proliferation, migration, and invasion of the tumor cells." (PMID 34503058, 2021). "Functionally, miR-137 directly binds to CXCL12 to regulate cell invasion and angiogenesis in ovarian cancer." (PMID 34204094, 2021). "In ovarian cancer, CXCL12/CXCR4 signaling stimulated tumor angiogenesis, development of cancer-initiating cells and metastasis to the peritoneum via recruitment of immunosuppressive cells, such as regulatory T (Treg) cells." (PMID 34503058, 2021). "In particular, metapristone affected ovarian cancer metastasis through interrupting CXCL12/CXCR4 axis." (PMID 33413440, 2021). "In ovarian cancer cells, CXCL12 and its receptor CXCR4 increased the production of integrin-1β and vascular endothelial growth factor-C (VEGF-C), activating tumor vasculature in ovarian cancer." (PMID 34912809, 2021). "The overexpression of PGE2 in the microenvironment of ovarian cancer also induces the production of CXCL12 (SDF1), thereby enhances the migration of CD11b+CD14+CD33+CXCR4+MDSCs to the ascites of patients with ovarian cancer." (PMID 34689842, 2021). "It has also been reported that the inhibition of the CXCL12/CXCR4 pathways improves survival in ovarian cancer cells by preventing immunosuppression." (PMID 34307366, 2021). "The CXCL12/CXCR4 axis is also involved in the recruitment of immature pDCs in ovarian cancer where high levels of CXCL12 are produced by epithelial tumor cells." (PMID 32486257, 2020). "In ovarian cancer, CXCR4 and CXCL12 overexpression is linked with tumor cell proliferation and the CXCL12/CXCR4 signaling affects the anti-tumor immunity." (PMID 33096815, 2020). "Consistently, it was reported that CXCL12/CXCR4 axis triggered PGE2-induced accumulation of MDSCs in ovarian cancer microenvironment." (PMID 30678736, 2019).
ovarian carcinoma (continued). "We also found lowest amount of CXCL12 in the serum of combination treatment group, which is in line with the previous finding that CXCL12 levels in serum are correlated with ovarian cancer prognosis." (PMID 31320999, 2019). "In depth, the functional expression of CXCR4 in IGROV and CAOV-3 ovarian cancer cells were demonstrated by the presence of CXCL12-induced Ca2+ transients." (PMID 31703453, 2019). "The Notch pathway has also been found to promote ovarian cancer growth and migration via the CXCL12/CXCR4 chemokine system." (PMID 31382985, 2019). "Ovarian cancer cell expression HOXA9 induces CAFs to secrete CXCL12, IL-6, and VEGF-A expression, which promotes angiogenesis." (PMID 30380628, 2018). "Another study suggested that PGE2 regulates CXCL12 levels in malignant ascites from ovarian cancer patients and CXCR4 expression on MDSC." (PMID 30319622, 2018). "The activation of CXCR4 results in the upregulation of the prometastatic cytokines IL-6, CXCL12, and TNFα in ovarian cancer cells and increases metastasis." (PMID 28275576, 2017). "It was reported that an autocrine inflammatory cytokine network of inflammatory cytokine TNF-α, angiogenic factor VEGF, and chemokine CXCL12 existed in ovarian cancer microenvironment and stimulated tumor neoangiogenesis." (PMID 25887589, 2015). "The exposure to >10 μM genistein downregulated CXCR4, inhibiting chemotaxis and chemoinvasion of breast and ovarian cancer cells towards CXCL12." (PMID 26703550, 2015). "The same dual effect of genistein was observed for the C-X-C chemokine receptor type 4 (CXCR4) and C-X-C motif chemokine 12 (CXCL12) levels in breast and ovarian cancer cells." (PMID 26703550, 2015). "Another report showed that the growth and metastasis of ovarian cancer cells expressing CXCR4 under suboptimal culture conditions were stimulated by the ligand CXCL12." (PMID 26083776, 2015). "We compared the mRNA expression of CXCR3, CXCL-10, CXCR4, CXCL-12, IL-4, and IL-10 in tissues of benign and malignant ovarian tumors by qRT-PCR method and evaluated serum IL-10 and CA-125 content of these patients by ELISA during one year." (PMID 25999622, 2015). "The results of the present study also confirmed that LPA increased the content of CXCL12 in the supernatant of ovarian carcinoma cells and enhanced the proliferation, migration and invasion of the ovarian cancer cells, SKOV3 and CAOV3." (PMID 24765180, 2014). "A recent study demonstrated that all 289 ovarian cancer patients analyzed expressed CXCL12, and the rate of CXCR4 expression was 69%; thus CXCL12 can serve as an independent prognostic indicator for ovarian cancer." (PMID 24765180, 2014). "Following treatment with 100 ng/ml CXCL12 for 24 h, the migration rates of the ovarian cancer cells, CAOV3 and SKOV3, were significantly increased compared with the control group (P<0.0001 and P=0.005, respectively)." (PMID 24765180, 2014). "In a previous study on ovarian cancer, out of 14 chemokine receptors only CXCR4 was expressed on the ovarian cancer surface, and CXCL12 was detected in the ascites of 63 patients." (PMID 24765180, 2014). "Ovarian cancer cells secrete SDF-1α/CXCL12, which led to the suggestion that through such mechanisms plasmacytoid dendritic cell precursors are recruited resulting in poor T cell activation." (PMID 25251539, 2014). "LPA (20 μM) and CXCL12 (100 ng/ml) enhanced the proliferation, migration and invasion of the ovarian cancer cells, CAOV3 and SKOV3, as identified by MTT, Transwell and Matrigel assays following co-treatment for 24 h." (PMID 24765180, 2014). "In mouse models, we and others have shown that blocking CXCL12-CXCR4 signaling with RNA interference against CXCL12 or a small molecule inhibitor of CXCL12-CXCR4 binding (AMD3100) limits growth of ovarian cancer cell implants." (PMID 23372646, 2013).
ovarian carcinoma (continued). "Frequencies of MDSCs closely correlated with CXCL12 and PGE-2 levels in ascitic fluid, and inhibition of COX-2 or PGE-2 receptors in MDSCs suppressed CXCR4 expression, and thus MDSC responsiveness to CXCL12 or ovarian cancer ascites." (PMID 23508517, 2013). "CXCL12 is secreted by ≈70–90% of ovarian cancer cells, as well as mesothelial cells within the peritoneum of humans and mice." (PMID 23372646, 2013). "Others and we have found that CXCR4 is overexpressed in specimens of human ovarian cancer, and its specific ligand CXCL12 is present in the ascitic fluid collected from patients with ovarian carcinoma." (PMID 24384839, 2013). "Chemokine CXCL12 (SDF-1) and its receptor CXCR4 are strongly implicated as key determinants of tumor initiation and intraperitoneal metastasis of ovarian cancer." (PMID 23372646, 2013). "We tested protective effects of CXCL12 against cytotoxicity from cisplatin, a standard chemotherapeutic drug for ovarian cancer." (PMID 23372646, 2013). "Patients with the highest levels of CXCL12 expression in ovarian cancer cells have a significantly worse prognosis, emphasizing the biologic significance of this signaling molecule in disease progression." (PMID 23372646, 2013). "Effects of CXCL12 on ovarian cancer appear to be mediated by CXCR4, one of two known receptors for this chemokine." (PMID 23372646, 2013). "It has been shown that CXCL12 elicits intracellular calcium influx, resulting in chemotaxis, increased cell proliferation, and changes in β1 integrin expression in ovarian cancer cells." (PMID 24384839, 2013). "Ovarian cancer cells express CXCR4 and consistently, high concentrations of CXCL12 are detectable in the ascites and tumor masses of ovarian cancer patients, suggesting that this axis accelerates cancer dissemination in the peritoneal cavity." (PMID 24213462, 2012). "Various tumours, in particular the androgen-dependent tumours such as prostate, breast and ovarian cancers, produce CXCL12 and express CXCR4." (PMID 22415233, 2012). "In conclusion, this study has shown that expression of CXCL12 is an independent prognostic indicator of poor survival in ovarian cancer." (PMID 22415233, 2012). "The results demonstrate that expression of high levels of CXCL12 is an independent marker of poor prognosis in ovarian cancer." (PMID 22415233, 2012). "Its ligand, CXCL12 (stromal cell-derived factor 1), in ovarian cancer cells stimulates cell migration and invasion through extracellular matrix, as well as DNA synthesis and EGFR transactivation." (PMID 23905066, 2012). "This study demonstrated reduced disease-specific survival (P=0.026) in ovarian cancer patients whose tumours showed moderate or high CXCL12 expression." (PMID 22415233, 2012). "It should be noted that CXCL12 expresses not only in advanced stage ovarian cancers but also in Stage I and II cancers." (PMID 24213462, 2012). "The prognostic significance of CXCL12 production by ovarian cancer cells remains to be clearly assessed in larger cohorts of EOC patients undergoing the same type of chemotherapy and followed up for longer periods." (PMID 21410972, 2011). "CXCL12 is present in ascites and is expressed by peritoneal mesothelial cells, thus explaining that in part, migration and attachment of ovarian cancer cells to the peritoneum are facilitated by CXCL12–CXCR4 interactions." (PMID 22022379, 2011). "We evaluated the prognostic value of CXCL12 for EOC, by quantifying CXCL12 staining in 183 ovarian cancer specimens." (PMID 21410972, 2011). "CXCL12 was assayed in the culture medium of three ovarian cancer cell lines, SKOV-3, OVCAR-3 and BG-1, and in malignant ascites." (PMID 21410972, 2011). "CXCL12, which stimulates ovarian cancer cell invasion, was amplified and has been shown to be expressed in ovarian cancer but not normal ovaries or ovarian surface epithelium." (PMID 22194851, 2011).
ovarian carcinoma (continued). "Thus, even if the published studies individually examined a small number of ovarian cancers, all these results agree that CXCL12/CXCR4 axis may be closely associated with the development of peritoneal metastasis and the prognosis of patients with epithelial ovarian carcinoma (EOC)." (PMID 20049170, 2010). "In these types of cancer, distant metastasis, favored by CXCL12 expression on target organs, significantly influences the survival, while in ovarian cancer the recurrence in the pelvis and in the peritoneum is the main cause for death." (PMID 20049170, 2010). "We also demonstrate that like DIM, genistein specifically inhibitschemotaxis and chemoinvasion of breast and ovarian cancer cells toward CXCL12 in vitro." (PMID 19325924, 2009). "Similar to our previous work with the chemoprotective phytochemical, 3,3′-diindolylmethane (DIM), we show here that genistein also downregulates CXCR4 and CXCL12 and subsequently lowers the migratory and invasive potentials of breast and ovarian cancer cells." (PMID 19325924, 2009). "Biologically,significant CXCL12 levels have beenfound in peritoneal ascites from ovarian cancer patients, pleuraleffusions in lung cancer, lymph nodes, bone, and lungs as well as othertissues." (PMID 18779872, 2008). "One of the most studied chemokine pathways in ovarian cancer is the CXCL12/CXCR4 axis." (PMID 40362280, 2025). "Furthermore, an investigation into the correlation between CXCL12 genetic alternations and clinical survival outcomes in ovarian cancer revealed poorer prognoses amongst patients with altered CXCL12." (PMID 40166682, 2025). "R54 inhibited ovarian cancer cells proliferation and migration CXCL12-induced." (PMID 39700131, 2024). "As R54 impairs mesenchymal transition CXCL12 induced, the study suggests that R54 may be added to chemotherapy treatment of ovarian cancer to reduce mesenchymal features such as migration/ invasiveness and increase chemotherapy sensitivity." (PMID 39700131, 2024). "Moreover, R54 inhibited CXCL12 dependent pERK1/2 and pAKT and reversed the CXCL12 induced EMT in ovarian cancer cells." (PMID 39700131, 2024). "CXCL12 is an alpha-chemokine ligand specific for the CXCR4 receptor, and the CXCL12/CXCR4 axis was found to be activated by cancer-associated fibroblasts to promote epithelial–mesenchymal transition and cisplatin resistance in ovarian cancer." (PMID 37270714, 2024). "In addition to CXCL12 and CXCL8, other chemokines have been implicated in ovarian cancer progression." (PMID 37762405, 2023). "This study aimed to evaluate the expression of CXCL12 in primary and recurrent epithelial ovarian cancer tissue and explore whether its assignability to tumor/immune cells affects chemosensitivity or prognostic survival." (PMID 37966614, 2023). "The survival advantage in our cohort due to the high endogenous expression of CXCL12 in the recurrent group may be due to the inability of ovarian cancer cells to migrate and metastasize." (PMID 37966614, 2023). "For inhibition of the recruitment of TAMs, the CCL2/CCR2 axis barricade which is has been found to be helpful in a mouse ovarian cancer model, and disrupting the CXCL12/CXCR4 axis which prolongs the survival of a tumor mouse model seem to be an encouraging therapy." (PMID 36341388, 2022). "CXCL12/CXCR4 also enhances cell migration to promote the progression of human ovarian cancer." (PMID 35893797, 2022). "CXCL12 is an independent predictor of poor survival in ovarian cancer." (PMID 35406620, 2022). "Moreover, lncRNA SCAMP1 can bind with miR-137 and upregulate the expression of CXCL12 (C-X-C motif chemokine ligand 12) in ovarian cancer cells." (PMID 35992869, 2022). "For the exosomes of both studied cell lines, after treatment with α-mangostin and cisplatin simultaneously, a two-fold lower increase in the expression of the CXCL12 gene was observed (in relation to the treatment of fibroblasts with exosomes from untreated ovarian cancer cells)." (PMID 36012171, 2022).
ovarian carcinoma (continued). "In epithelial ovarian cancer, the elevated expression of STAT4 in epithelial cells induced MSCs derived from adipose and bone marrow to obtain CAF-like features, which in turn promoted EMT and peritoneal metastasis of ovarian cancer by secreting CXCL12, IL-6 and VEGF-A." (PMID 36185262, 2022). "Thus, although no prognostic factors were identified through objective and rigorous statistical methods with ovarian cancer clinical data, the data support the rationale for CXCL12 targeting therapy in EOC management." (PMID 35406620, 2022). "A high level of CXCL12 is an independent predictor of poor survival in ovarian cancer." (PMID 32337262, 2020). "Moreover, high levels of CXCL12 were detected in ascitic fluid from patients with ovarian cancer, and some authors proposed the CXCR4/CXCL12 pair as a molecular target in ovarian cancer." (PMID 31703453, 2019). "Besides FAPα, CAF-derived SDF-1, also known as CXCL12, has been shown to promote tumor growth, motility, and tumor angiogenesis in multiple cancer types, including ovarian cancer, by interacting with the CXCR4 receptors on cancer cells." (PMID 26751490, 2016). "For example, CXCL12 promoted cell migration, cell growth, and invasion of ovarian cancer cells." (PMID 25990390, 2015). "Moreover, OVCAR-5 CXCR4+CD133+ cells migrated toward the CXCR4 ligand CXCL12, were less sensitive to the most popular chemotherapeutic agent utilized in ovarian cancer, cisplatin, and over expressed the drug resistance transporter ABCG2." (PMID 26020117, 2015). "The expression of CXCR4 and CXCL12 was increased in the ovarian cancer cells in a dose- and time-dependent manner when treated with LPA compared with the control groups (P<0.05), as determined by reverse transcription polymerase chain reaction and flow cytometry." (PMID 24765180, 2014). "Adverse effects of CXCL12 on ovarian cancer also may be due to effects on the stromal compartment of the tumor microenvironment, including enhanced angiogenesis and recruitment of immunosuppressive cells." (PMID 23372646, 2013). "In a recent study, it was shown that PGE-2 attracts MDSC into the ascites microenvironment of ovarian cancer patients by inducing expression of functional CXCR4 in cancer-associated MDSCs, and plays a role in the production of its ligand CXCL12, thus ensuring MDSC migration." (PMID 23508517, 2013). "The advantage of the CXCR4-β-arrestin 2 reporter is that this system quantifies activation of CXCR4 in ovarian cancer cells by all sources of CXCL12 in the tumor microenvironment, while our previous assay detected only CXCL12 engineered with a fusion protein for complementation imaging." (PMID 23372646, 2013). "While parental HeyA8 cells do not express CXCL12 as determined by QRT-PCR (data not shown), HeyA8-CXCL12-GL cells secrete approximately 12 ng/ml CXCL12 in a 24 hour period, which is comparable to values reported for other ovarian cancer cells that secrete this chemokine endogenously." (PMID 23372646, 2013). "In addition to direct effects on ovarian cancer cells, CXCL12 and CXCR4 regulate key components of the tumor microenvironment." (PMID 23372646, 2013). "Additional studies show that the CXCR4/CXCL12 axis in ovarian cancer may promote peritoneal metastasis as well as metastasis to the lymph nodes." (PMID 24259307, 2013). "The chemokine CXCL12 is an independent predictor of poor survival in ovarian cancer." (PMID 22415233, 2012). "Porcile found that CXCL12 induced EGFR phosphorylation in ovarian cancer cells." (PMID 22848341, 2012). "CXCL12 was abundantly expressed within biopsy and ascite samples from ovarian cancer patients." (PMID 22415233, 2012). "Using a tissue microarray of 289 primary ovarian cancers coupled to a comprehensive database of clinicopathological variables, the expression of CXCL12 and CXCR4 was assessed by immunohistochemistry and its impact in terms of survival and clinicopathological variables was determined." (PMID 22415233, 2012).